CCL17 (C-C motif chemokine ligand 17)
Diseases named in the same sentence as CCL17 in open-access papers (continued):
Sharing a sentence is not in itself a finding about the gene and the disease.
asthma (continued). "There have also been reports of CCL-17 (found at higher levels in asthma BAL compared with normal controls) being a ligand for CCR8, although this observation was not supported by another group." (PMID 20455898, 2010). "Asthma and allergies were significantly associated with CCL20 and CCL17, p < 0.03, respectively." (PMID 40181810, 2025). "The marked upregulation of IL1B and CCL17 indicates that the overexpression of these genes may directly influence immune responses in asthma patients." (PMID 40309741, 2025). "Similarly, the elevation of CCL17 amplifies the inflammatory response by recruiting Th2 cells, contributing to a persistent state of chronic inflammation in asthma patients." (PMID 40309741, 2025). "Moreover, HDM + O3 exposure induced a significantly greater gene expression of Ccl17 that has pleiotropic roles in allergic inflammation/asthma in part through TH17 cell recruitment." (PMID 39244793, 2024). "Increased serum levels of the chemokine CCL26/eotaxin-3 could differentiate moderate-to-severe asthma from healthy controls, and recent findings point out the ability of CCL17/TARC to predict type-2 eosinophilic asthma." (PMID 36835081, 2023). "Cytokines including interleukin 4 (IL-4), interleukin 5 (IL-5), IL-6, IL-8, interleukin 10 (IL-10), monocyte chemoattractant protein (MCP)-1/CCL2, and thymus and activation-regulated chemokine (TARC)/CCL17 trigger secondary inflammatory events, aggravating asthma pathogenesis." (PMID 29755573, 2018). "Since our data links macrophage ALOX15B to CCL17 production and T cell migration, we reasoned whether these findings might be relevant to human asthma." (PMID 30197642, 2018). "In patients with asthma, CCL17 has been found in increased concentrations in serum and BALF." (PMID 25849971, 2015). "An in vivo study was run in the A. fumigatus chronic fungal asthma model to determine whether any difference in neutralizing activity could be seen based on targeting either CCL17 alone or targeting both CCL17 and CCL22." (PMID 24339934, 2013). "Studies of endobronchial biopsy specimens and BAL fluid of subjects with severe asthma have shown that asthma is associated with elevated bronchial mucosal expression of TSLP and Th1-attracting (IP-10/CXCL10) and Th2-attracting (TARC/CCL17, MDC/CCL22) chemokines." (PMID 22523502, 2012). "Furthermore, HZ-1127 dramatically inhibits TSLP-dependent STAT5 activation and is more potent than Tezepelumab, which is an FDA-approved humanized mAb against TSLP for severe asthma treatment in inhibiting TSLP-induced CCL17 and CCL22 chemokines secretion in human peripheral blood mononuclear cells." (PMID 38566968, 2024). "In mice, CCL17 has been linked with various inflammatory conditions presumably by setting the stage for a Th2 response through recruitment of CCR4+ immune cells, from controlling schistosomiasis and colitis to conditions of chronic pulmonary inflammation seen in fibrosis and asthma models." (PMID 24339934, 2013). "Whole-transcriptome sequencing identified key inflammatory genes, such as IL1B, CCL17, and MUC5AC, that were upregulated in asthma patients, while immune regulatory factors like FOXP3 and IFNG were higher in healthy controls." (PMID 40309741, 2025). "In vitro, knocking down Kif3a increased epithelial apoptosis, boosted CCL17, IL‐5, and IL‐8 transcription, and raised COX‐2 protein levels and β‐catenin translocation; Conversely, Kif3a overexpression greatly alleviates asthma." (PMID 39949885, 2025). "Galectin-9 has demonstrated efficacy in a Dermatophagoides farinae allergen-induced asthma model by suppressing the expression of IL5, IL13, CCL11, CCL17, reducing eosinophilia, and pulmonary hyperresponsiveness." (PMID 41516283, 2025). "CCL17 and CCL22 have been studied as potential therapeutic targets for type 2 inflammatory diseases, including asthma." (PMID 39508721, 2024).
asthma (continued). "In TSLP/OVA induced asthma model, the intranasal administration of TSLP/OVA significantly induced the elevation of serum IgE level and key inflammatory cytokines CCL17 and IL-13 levels in the lung which contributed to the disease establishment and progression." (PMID 39726595, 2024). "IL‐5, CCL17, CCL26 and TSLP concentrations were elevated significantly in asthma overall compared with health." (PMID 35579040, 2022). "We examined serum chemokine (CCL4, CCL11, CCL26, and CCL17) and total IgE serum levels, fractionated exhaled nitrogen oxide (FENO), and CCL4 expression in nasal polyps in patients with severe ECRS and asthma." (PMID 35892679, 2022). "Total serum IgE and the levels of BALF Th2 cytokines/chemokines such as CCL17, CCL22, IL-13, IL-17, and periostin were elevated in the severe asthma mice compared to the saline-treated control." (PMID 35958610, 2022). "CCL17 and TSLP concentrations were increased in T2‐high‐FNS and T2‐intermediate asthma compared with healthy controls, but similar across the asthma groups." (PMID 35579040, 2022). "This asthma-associated composition furthermore correlated with lower levels of topical pro-inflammatory airway immune mediators (IL-1β and TNF-α), which may characterize an inefficient anti-bacterial response, and higher levels of monocyte and T-cell recruiting chemoattractants (CCL2 and CCL17)." (PMID 31676759, 2019). "The importance of CCL17 and CCL22 is furthermore confirmed in murine asthma models where their neutralization with specific antibodies resulted in attenuation of AHR and airway inflammation." (PMID 28894452, 2017). "This study provides evidence for an augmented expression of CCL13, CCL17, and CLEC10A in AMΦ from patients with mild asthma during episodes of acute allergic airway inflammation." (PMID 24612750, 2014). "Genes such as IL1B and CCL17 exhibited significantly upregulated expression in the patient group, while others, like IFNG and FOXP3, were markedly downregulated (p < 0.05), suggesting their potential roles in asthma pathogenesis." (PMID 40309741, 2025). "Additionally, we examined the levels of inflammatory cytokines in sputum and found that IL‐5, IL‐6, IL‐8, TNF‐α, IFN‐γ, CCL17, CCL22, CXCL10, CCL4, CCL2, IL‐4, IL‐13, and CCL26 were significantly lower in stable asthma than in acute asthma." (PMID 39508721, 2024). "Among these, only CCL17 displayed a stronger non-specific relationship with allergic asthma when compared to the value obtained for the asthma evaluation." (PMID 33936056, 2021). "The researchers found that the expression of mRNA-encoding TSLP, TARC/CCL17, MDC/CCL22 and IP-10/CXCL10, other than I-TAC/CXCL11 and I-309/CCL1, were significantly increased in severe asthma and COPD patients compared to the non-smoking control group." (PMID 34301307, 2021). "Furthermore, in a murine asthma model, CCL22 or CCL17 neutralization decreased eosinophilic airway inflammation and ameliorated allergic symptoms." (PMID 30405619, 2018). "Increased levels of CCL17 were found in BALF, plasma/serum and sputum of patients with asthma." (PMID 30405619, 2018). "In addition to CCL11/eotaixn-1 and TNF-alpha, HBEC exposed to TSLP induced the secretion of CCL22/MDC and CCL17/TARC, two CCR4-ligands that are considered critical Th2-related chemokines in asthma exacerbations." (PMID 25546419, 2014). "Rapamycin did not alter mRNA levels of CCL17 (TARC) in either the induction or treatment models of HDM-induced asthma." (PMID 22685525, 2012). "However, it remains unclear whether STAT6 and/or NF‐κB influence the development of pulmonary CCL17 and CCL22 in the context of rhinovirus (RV) infection and asthma." (PMID 39508721, 2024). "An obvious potential caveat of total CCR4 blockade as an asthma treatment is the potential for the impairment of regulatory T cell recruitment, since T-regulatory cells (Tregs) have been shown to express CCR4 and to migrate in vitro in response to both CCL17 and CCL22." (PMID 25981299, 2015).
asthma (continued). "Despite a trend for CCL17 protein being higher in these two participants, all other macrophage responses to IL-4, IL-13, and combined IL-4/IL-13 stimulation fell within the range of responses seen in donors without asthma and did not skew the overall dataset, justifying their inclusion." (PMID 41159038, 2025).
allergic disease (38 papers, 2008 to 2026). An immune response that occurs following re-exposure to an innocuous antigen, and that requires the presence of existing antibodies against that antigen. "In vivo, the BsAb TAVO101 × IL4R-dupi reduced all hallmark features of allergic disease, including IgE production, IL-5 and CCL17 levels, eosinophilic infiltration, and mucus hypersecretion." (PMID 41294800, 2025). "CCL17 levels were lower among exposed workers and workers with allergies, and those who reported acute upper respiratory symptoms while reported chronic lower respiratory symptoms were associated with higher CCL17 levels." (PMID 40181810, 2025). "TSLP can stimulate the activation of primary human CD1c+ dendritic cells with the increased secretion of CCL17, a chemokine which is involved in many allergy and inflammation reactions." (PMID 39726595, 2024). "Th9 cells were initially studied in allergic diseases and autoimmune diseases, and they promote the development of allergic diseases by promoting the expression of the Th2 cell-related chemokines CCL17 and CCL22." (PMID 32228589, 2020). "After adjusting the model according to maternal allergy, the CB CCL17 level remained an independent factor that significantly correlated to CP-DEI, whereas family size and cat ownership during pregnancy were inversely correlated to CP-DEI." (PMID 31719945, 2019). "This indicates that dietary GOS facilitates budesonide treatment in its capacity to further decrease allergy driving mediators IL-33, CCL17 and CCL22, derived from both airway epithelial cells and DC." (PMID 30405619, 2018). "Budesonide significantly decreased the HDM allergy-induced levels of CCL17, whereas 1% GOS showed a reduction of >20%." (PMID 25849971, 2015). "The role of PTGDR2 and CCL17 (TARC) in the pathogenesis of allergic disease is well‐recognized." (PMID 34637606, 2022). "Moreover, during pregnancy, CCL17 is produced by the conceptus, and higher CB CCL17 levels precede AD in infancy and allergy development in childhood." (PMID 34444997, 2021). "Additionally, both OX‐40L and CCL17 in DCs can trigger Th2 polarization, which induces a low inflammatory response and plays a protective role in allergy under the effect of thymic stromal lymphopoietin." (PMID 32406154, 2020). "A CCL17 gene is a candidate as one of the genetic factors in some allergic diseases." (PMID 29364829, 2018). "The predominant expression of CCR4 in Th2 cells, as well as the upregulation of CCL17 and CCL22 in allergic diseases, have captured attention for their potential therapeutic targeting of CCR4 in the treatment of allergies." (PMID 33669094, 2021). "TARC is a chemokine belonging to the CC chemokine family, namely CCL17, and is produced by immune cells in allergic diseases." (PMID 34299145, 2021). "It is well known that the CCR4 and its ligands CCL17 and CCL22 played an important role in allergic diseases." (PMID 29118379, 2017). "CCL24, CCL17 and CCL22 were increased in OVA immunized mice in comparison to the adjuvant immunized mice as expected in the current model for allergy." (PMID 27580126, 2016). "According to these studies, targeting the interactions between CCL17/CCL22 and CCR4 may be a useful approach for controlling allergic diseases." (PMID 30718772, 2019). "Moreover, high cord blood levels of CCL17 and CCL22 were shown to precede allergy development during the first 6 years of life." (PMID 29966024, 2018). "Notably, the decoy GPN279 and GPN136 molecules validate CCL17 and CCL22 as therapeutic targets in allergy and create a path for its potential to be realized." (PMID 26442456, 2015). "This indicates that there is a potential for molecules that could effectively and specifically neutralize CCL17 or CCL22 i) to help understand the role of CCL17 and/or CCL22, and ii) to develop new therapeutic strategies for allergic diseases." (PMID 26442456, 2015).
allergic disease (continued). "Although the reason for the later finding is not immediately apparent, the elevation in BALF IgE, IgG1, and lung ccl17 mRNA levels with live conidia inhalation suggests that viable conidia have a greater tendency to induce allergy than the nonviable conidia." (PMID 24063011, 2013).
melanoma (29 papers, 2016 to 2026). A malignant, usually aggressive tumor composed of atypical, neoplastic melanocytes. "CCL17 overexpression indicated tumor development and lung metastasis in a melanoma model with subcutaneous or intravenous melanoma cell injection, leading to an increased risk of malignant tumor development in the Th2-dominant immune environment." (PMID 36362231, 2022). "In breast cancer patients, increased CCL17 expression was associated with poorer survival, while in melanoma patients increased CCL17 levels corresponded to improved survival." (PMID 34503058, 2021). "Additionally, high serum levels of CCL17 have been associated with improved survival in human melanoma patients." (PMID 37762335, 2023). "Increased expression of CD8+ granzyme B+ T cells has been correlated with higher transcript levels of CCL17, and higher serum levels of CCL17 were also associated with progression-free survival in advanced melanoma patients undergoing dendritic-cell-based immunotherapy." (PMID 37762335, 2023). "Upregulation of Ccl17 by AM represents an anti-tumour trait, consistent with reports showing that increased serum levels of CCL17 are associated with improved survival of advanced melanoma patients." (PMID 36241867, 2022). "Specifically, the CCR4/CCL17 axis promotes melanoma cells to migrate toward astrocytes and TEM via the BBB." (PMID 37190188, 2023). "In advanced melanoma patients treated with dendritic cell-based therapy, high serum levels of CCL17 are related to improved progression-free survival." (PMID 35620481, 2022). "CCL17 can promote anti-CT26 tumour immune response, and high serum levels are associated with improved survival rates in advanced melanoma patients." (PMID 35226704, 2022). "A study from our laboratory established that the chemokine receptor CCR4 is a member of the molecular signature of melanoma brain metastasis and that its chemokine ligands CCL17 and CCL22 are expressed in microenvironmental brain cells." (PMID 32761606, 2021). "Cross talk between melanoma cells and microglia, astrocytes and brain endothelial cells (EC) upregulated CCR4 expression on melanoma cells and CCL17/CCL22 expression by and secretion from the brain cells." (PMID 32761606, 2021). "As expected, skin tumor formation by melanoma cells and lymphoma cells was significantly enhanced in CCL17 TG mice compared with wild-type (WT) mice." (PMID 33670758, 2021). "Tumor formation and lung metastasis were accelerated in CCL17 TG mice when melanoma cells were injected subcutaneously or intravenously." (PMID 33670758, 2021). "In contrast, an increased expression of CCL22 in the tumor improves prognosis in lung cancer patients and elevated CCL17 blood levels improve prognosis in melanoma patients." (PMID 33182504, 2020). "This was confirmed in an antibody-based neutralization of CCL17 in vitro, which attenuated melanoma cell migration and transendothelial migration." (PMID 30053879, 2018). "CCL17 was sufficient to enhance melanoma cell invasiveness, and neutralizing this ligand in astrocyte-conditioned medium attenuated the astrocyte-mediated migration of melanoma cells." (PMID 28415693, 2017). "Repolarizing TAMs by immunomodulators such as imiquimod and IFNs may inhibit melanoma tumor growth as TAMs generated by CCL17 and CCL22 attract Tregs to melanoma tumor locations." (PMID 37525217, 2023). "The roles of KCNE4 in chemokine production and cell adhesion were examined using primary lymphatic endothelial cells, and demonstrated that Ccl17 and Ccl19, which are involved in melanoma metastasis, were upregulated by KCNE4, as well as Mmp3 matrix metalloproteinase." (PMID 35915077, 2022). "In addition, lung metastasis, made by intravenous injection of melanoma cells, was significantly augmented in CCL17 TG mice." (PMID 33670758, 2021).